ANLN (anillin, actin binding protein)
Diseases named in the same sentence as ANLN in open-access papers (continued):
Sharing a sentence is not in itself a finding about the gene and the disease.
liver cancer (9 papers, 2018 to 2025). An epithelial or non-epithelial malignant neoplasm that arises from the liver. "Multiple bioinformatics studies have shown that ANLN expression is closely associated with the occurrence, development, and prognosis of liver cancer." (PMID 41573677, 2025). "Increasing evidence shows that ANLN is aberrantly overexpressed in various cancers, including lung, breast, and liver cancers, and that its elevated expression is associated with enhanced tumor cell proliferation, migration, and invasion." (PMID 41573677, 2025). "The mechanistic role of ANLN in liver cancer is particularly evident in its involvement in metastasis-driving pathways." (PMID 41573677, 2025). "Knockdown of ANLN in H2.35 hepatocytes using a small interfering RNA resulted in increased expression levels of ANLN mRNA in human liver cancer tissues; furthermore, the cytoplasmic division was blocked, which inhibited the development of liver tumors." (PMID 34194957, 2021). "ANLN with the m6A modification has a crucial function in liver cancer bone metastasis." (PMID 38398143, 2024). "Notably, and in agreement with what was observed in the mouse models of liver cancer, ANLN, HMMR, TPX2, CCNB1, and CCNB2 expressions were found to be significantly upregulated in TCGA-LIHC." (PMID 37566034, 2023). "The number of ANLN genes in liver cancer cells affects cell division." (PMID 34194957, 2021). "In liver cancer, ANLN promotes PLK1-mediated phosphorylation of RACGAP1 and subsequent activation of RhoA, thereby ensuring mitotic accuracy, whereas ANLN inhibition disrupts mitosis and effectively suppresses tumor growth." (PMID 41573677, 2025). "Notably, ANLN depletion increases polyploidy in hepatocytes, a process thought to confer resistance to carcinogenic insults while preserving genomic integrity without inducing regeneration defects or non-diploid risks—suggesting a potentially protective role in liver cancer development." (PMID 41573677, 2025). "Moreover, ANLN expression level was significantly correlated with OS (P = 2.6e−05), DFS (P = 8.7e−06), RFS (P = 3.6e−06), and PPS (P = 5.2e−08) in patients with liver cancer." (PMID 35568883, 2022).
bladder urothelial carcinoma (8 papers, 2017 to 2022). "Transcriptome sequencing identified ANLN as a potential prognostic biomarker in bladder urothelial carcinoma." (PMID 32560530, 2020). "For example, ANLN was upregulated in bladder urothelial carcinoma, and elevated ANLN expression was correlated with poor progression-free and recurrence-free survival." (PMID 31395079, 2019). "For example, ANLN knockdown inhibited cell proliferation and metastasis and induced G2/M arrest in bladder urothelial carcinoma." (PMID 31395079, 2019). "Consistent with our results, ANLN knockdown significantly repressed cell proliferation, migration and invasion in bladder urothelial carcinoma." (PMID 31395079, 2019). "In addition, the role of ANLN in bladder urothelial carcinoma growth was tested on J82 and 5637 cells by making a comparison between ANLN knockdown and control groups." (PMID 32560530, 2020). "Interestingly, ANLN downregulation inhibited not only cell proliferation, but also migration and invasion in bladder urothelial carcinoma, implying a role of ANLN beyond cell cycle regulation." (PMID 30103211, 2018). "Moreover, in bladder urothelial carcinoma and LUAD, alterations observed in TCGA datasets included mutations, amplifications, multiple alterations, deep deletions, and structural variants; missense mutations were the main types of ANLN mutations." (PMID 35568883, 2022).
esophageal squamous cell carcinoma (7 papers, 2022 to 2026). Esophageal squamous cell carcinoma (ESCC) is a type of esophageal carcinoma (EC) that can affect any part of the esophagus, but is usually located in the upper or middle third. "ANLN is highly expressed in esophageal squamous cell carcinoma(ESCC), and its elevated expression is associated with poor prognosis in patients with ESCC." (PMID 41573677, 2025). "Here, we show that high expression of ANLN promotes cytokinesis and proliferation in esophageal squamous cell carcinoma (ESCC) cells and is associated with poor prognosis in ESCC patients." (PMID 36526897, 2023). "It has been reported that increased ANLN expression promotes cytokinesis and proliferation in cells of esophageal squamous cell carcinoma, and is linked to a negative prognosis in patients with esophageal squamous cell carcinoma (ESCC)." (PMID 41438689, 2026). "Here, we reveal ANLN plays a crucial role in cell division of esophageal squamous cell carcinoma (ESCC) and identify USP10 as a novel DUB for ANLN." (PMID 36526897, 2023). "On the contrary, in esophageal squamous cell carcinoma (ESCC) and OV, patients with ANLN high expression had significant and favourable survival outcomes." (PMID 36199577, 2022). "The oncogene ANLN could be targeted and enhanced by USP10, leading to inferior prognosis for patients with esophageal squamous cell carcinoma." (PMID 40672387, 2025).
lymph node metastasis (7 papers, 2019 to 2026). "It is also positively correlated with high-grade tumors, advanced TNM stage, lymph node metastasis, vascular invasion, and tumor necrosis in urothelial carcinoma, with nuclear ANLN expression showing a stronger association in upper tract urothelial carcinoma(UCUT)." (PMID 41573677, 2025). "In addition, univariate analysis indicated that the TNM stage, lymph node metastasis and upregulated ANLN expression were associated with overall survival (P = 0.002, P = 0.016 and P = 0.034, respectively)." (PMID 31395079, 2019). "In this cohort, univariate analyses indicated that better OS is related with female and worse RFS is related to increased tumor size, microvascular invasion, perineural invasion, lymph node metastasis and elevated ANLN expression." (PMID 41513610, 2026). "The multivariate analyses illustrated that better OS is related with female and decreased tumor size, and worse RFS is related with increased tumor size, lymph node metastasis, and elevated ANLN expression." (PMID 41513610, 2026). "Multivariate analysis showed that the TNM stage, lymph node metastasis and upregulated ANLN expression were independent prognostic factors for overall survival (P = 0.001, P = 0.021 and P = 0.002, respectively)." (PMID 31395079, 2019). "The expression levels of ANLN and ARNTL2 were higher in men and patients with lymph node metastasis." (PMID 33585490, 2021). "Next, we proceeded to explore the relationship between the expression of RHOV, ANLN, PTTG1, DLGAP5, and FAM83A with pathological stage and lymph node metastasis, and the results showed that the transcriptional expression of the five prognostic features progressively increased with the stage." (PMID 39144144, 2024). "ANLN and PDGFD were differentially expressed between carcinoma without and with lymph node metastasis." (PMID 36362041, 2022). "ANLN and PDGFD were significantly upregulated in CRC with lymph node metastases when compared to those without lymph node metastases and can be considered as potential biomarkers for metastases in CRC." (PMID 36362041, 2022). "Similarly to PDGFD, in our research, ANLN was upregulated in CRC with lymph node metastases when compared to normal mucosa and to CRC without lymph node metastases and positively correlated with the level of malignancy." (PMID 36362041, 2022).
non-small cell lung carcinoma (7 papers, 2009 to 2025). A group of at least three distinct histological types of lung cancer, including non-small cell squamous cell carcinoma, adenocarcinoma, and large cell carcinoma. "In non-small cell lung cancer cells, ANLN downregulation induced cell growth repression, and ANLN overexpression promoted cell motility." (PMID 31395079, 2019). "In another study, depletion of ANLN expression in human non-small cell lung cancer cells leads to suppression of cell proliferation and multinucleated cell shape." (PMID 30103211, 2018). "In non-small cell lung cancer (NSCLC), nuclear localization of ANLN was associated with poor survival of patients with NSCLC." (PMID 28881803, 2017). "In non-small cell lung cancer, inhibition of the ANLN gene expression could suppress tumor cell growth, resulting in larger morphology, multiple nuclei, and ultimately cell death." (PMID 37051591, 2023). "In addition, the downregulation of phosphoinositide 3-kinase/AKT activity in non-small cell lung cancer cells leads to the instability of ANLN and induces a reduction in the ANLN level in the nucleus." (PMID 32560530, 2020). "The clonal cell lines in which PRC1, ANLN and YB1 are tagged originate from the same parental cell (H1299 non small cell lung cancer cell line)." (PMID 19381343, 2009).
prostate carcinoma (7 papers, 2015 to 2026). A carcinoma that arises from epithelial cells of the prostate gland. "Overexpression of ANLN in prostate cancer was significantly associated with poor prognosis and increased Gleason scores in patients." (PMID 41573677, 2025). "ANLN promotes the proliferation and migration of prostate cancer cells both in vitro and in vivo, and activates multiple signaling pathways to facilitate tumor development." (PMID 41573677, 2025). "Moreover, positive expression of ANLN has been shown to be a significant predictor of poor prognosis in prostate cancer patients." (PMID 41573677, 2025). "The regulatory pathways SOX5-NEDD4L/PBX3, miR429-GNAQ/ANLN—RHOA, and miR429-ANLN—KIF11 may participate in the progression of the androgen-independent phenotype in prostate cancer." (PMID 29324665, 2018). "They identified ANLN as a key gene containing a vitamin D response element(VDRE), which is highly expressed in prostate carcinoma tissues." (PMID 41573677, 2025). "Only two genes, ANLN and ECT2, were strongly correlated with prostate cancer prognosis and patients tended to have better survival rates when these genes were less active." (PMID 38785827, 2024). "In addition, ANLN could synergistically promote IGF2BP1-induced the protein stability of the proto-oncogene c-Myc and the activation of the MAPK signaling pathway, which accelerated prostate cancer growth." (PMID 41513610, 2026).
focal segmental glomerulosclerosis (6 papers, 2017 to 2022). A renal disorder characterized by sclerotic lesions in the glomeruli. "In humans, missense mutations in ANLN hinder the function of podocytes, epithelial cells of the glomerulus, causing focal segmental glomerulosclerosis (FSGS) and kidney failure." (PMID 35710398, 2022). "Mutations in ANLN have beendetected in patients with focal segmental glomerulosclerosis, and additionalexperiments have suggested that ANLN contributes to tumor progression." (PMID 34082790, 2021). "Deletion of ANLN caused nephrotic phenotype in zebrafish, and to date, two heterozygous mutations in the ANLN gene (c.1852G>T: p.G618C and c.1291C>T: p.R431C) have been reported in familial focal segmental glomerulosclerosis (FSGS) patients." (PMID 33915776, 2021). "In humans, a missense mutation in ANLN was identified as a cause of FSGS (focal segmental glomerulosclerosis; FSGS8, MIM 616032), which is characterized by segmental scarring of the glomerulus and is a leading cause of kidney failure." (PMID 30548429, 2019). "The kidneys from seven affected Dalmatians were histologically re-evaluated, since loss of ANLN function has been linked to human focal segmental glomerulosclerosis (FSGS)." (PMID 28222102, 2017). "ANLN has been previously linked to a dominant focal segmental glomerulosclerosis in human without pulmonary defects." (PMID 28222102, 2017).
head and neck squamous cell carcinoma (6 papers, 2021 to 2026). A squamous cell carcinoma that arises from any of the following anatomic sites: lip and oral cavity, nasal cavity, paranasal sinuses, pharynx, larynx, and salivary glands. "In head and neck squamous cell carcinoma, ANLN activates the ERK-MAPK pathway, thus upregulating PD-L1 level, which contributes to an immunosuppressive tumor environment." (PMID 41513610, 2026). "ANLN is significantly overexpressed in oral squamous cell carcinoma(OSCC), nasopharyngeal carcinoma(NPC), and head and neck squamous cell carcinoma(HNSCC)." (PMID 41573677, 2025).
triple-negative breast carcinoma (6 papers, 2015 to 2025). An invasive breast carcinoma which is negative for expression of estrogen receptor (ER), progesterone receptor (PR), and human epidermal growth factor receptor 2 (HER2). "In triple-negative breast cancer, ANLN enhances tumor stemness via the TWIST1–BMP2 axis, coordinates EMT-related transcriptional programs, promotes extracellular matrix degradation, and consequently facilitates tumor initiation and progression." (PMID 41573677, 2025). "ANLN is also upregulated in triple-negative breast cancer(TNBC), where it enhances cancer stemness and promotes sphere formation via the TWIST1 and BMP2 signaling pathways." (PMID 41573677, 2025). "Our results suggest a novel strategy for triple negative breast cancer control by concomitantly modulating ANLN and KDR gene expression while administrating Tamoxifen to triple negative patients." (PMID 31636652, 2019). "KDR and ANLN were positively correlated at the transcriptional level when ANLN gene expression was perturbed in triple negative breast cancer cell lines SUM159PT and MDAMB231." (PMID 31636652, 2019). "In contrast, super-enhancers found in triple-negative breast cancer (ER−, PR−, HER2−) co-localized with the transcription factors FOXC1, MET, MYC, and ANLN." (PMID 36232979, 2022). "The interaction between ANLN and KDR could act as ANLN and KDR jointly as a prognostic in cancer survival, which could be applied to control triple negative breast cancer." (PMID 32560530, 2020).
colon cancer (5 papers, 2018 to 2022). "It has been reported that the ANLN 210 mRNA was found in colon cancer cells secreted exosomes." (PMID 34344861, 2021). "Moreover, we noted that some of the mRNAs (ANLN, CFL2, FJX1, HHIP, PANX2, SCN3A, VSNL1 and ZIC2) were also associated with overall survival in patients with colon cancer." (PMID 29420609, 2018). "We observed the ANLN protein expression levels in ten cancer types and discovered that 9 out of 10 had higher ANLN protein expression than normal tissues, including BRCA, colon cancer, HNSC, KIRC LIHC, LUAD, OV, PAAD, and UCEC." (PMID 36199577, 2022).
nasopharyngeal carcinoma (5 papers, 2015 to 2025). A carcinoma arising from the nasopharyngeal epithelium. "The knockdown of ANLN suppressed cell proliferation and induced apoptosis in nasopharyngeal carcinoma (NPC) cells." (PMID 32560530, 2020). "Recent studies have indicated that miR-497, as a potent tumor suppressor, restrains cancer phenotypes via knockdown of ANLN and HSPA4L in nasopharyngeal carcinoma cells." (PMID 34743685, 2021).
ovarian carcinoma (5 papers, 2019 to 2022). A malignant neoplasm originating from the surface ovarian epithelium. "In ovarian cancer, high expression ANLN was associated with poor OS (P = 0.00038) and PPF (P = 0.01)." (PMID 35568883, 2022). "Contrastingly, among patients with glioblastoma and ovarian cancer, patients with high ANLN expression showed greater benefits from chemotherapy than those with low ANLN expression." (PMID 35991576, 2022). "In LUAD, CRC, and ovarian cancer, ANLN showed increased phosphorylation at S225, S755, S792, and S518." (PMID 35568883, 2022). "Like with CATS, elevated ANLN expression has been found in many human cancers, including in breast, endometrial, and ovarian cancers." (PMID 31756998, 2019). "The phosphorylation of ANLN protein was increased at phosphorylation site S182 in LUAD and UCEC and at S485 in ovarian cancer and UCEC." (PMID 35568883, 2022). "Total ANLN protein was evaluated using CPTAC datasets; the findings suggested that ANLN was upregulated in BLCA, ovarian cancer, COAD, LUAD, KIRC, and UCEC (P < 0.05)." (PMID 35568883, 2022). "We then identified significantly different phosphorylation sites in ANLN protein and assessed differences in the phosphorylation levels of ANLN between normal and tumor tissues using the CPTAC database for patients with BLCA, CRC, LUAD, UCEC, and ovarian cancer." (PMID 35568883, 2022).
pancreatic ductal adenocarcinoma (5 papers, 2017 to 2024). An infiltrating adenocarcinoma that arises from the epithelial cells of the pancreas. "Silencing the expression of ANLN could significantly inhibit the migration and invasion abilities of pancreatic ductal adenocarcinoma lines." (PMID 32903581, 2020).
glioblastoma (4 papers, 2022 to 2025). The most malignant astrocytic tumor (WHO grade IV). "Further analysis using the “CPTAC Analysis” confirmed ANLN overexpression in BRCA, renal cell carcinoma, COAD, HNSC, LIHC, LUAD, OV, PAAD, and UCEC tumors compared with in normal tissues; however, there was low ANLN expression in the glioblastoma multiforme." (PMID 35991576, 2022). "No ANLN expression difference was observed in glioblastoma multiforme (GBM) and kidney chromophobe (KICH)." (PMID 36199577, 2022).
glioma (4 papers, 2019 to 2026). A benign or malignant brain and spinal cord tumor that arises from glial cells (astrocytes, oligodendrocytes, ependymal cells). "ANLN gene encodes an actin-binding protein and regulates mitosis and cytokinesis in gliomas." (PMID 41438689, 2026). "The identified DryNB included seven genes (KIF2C, CCNA2, NDC80, KIF11, KIF23, ANLN and CENPM) that were significantly associated with drug sensitivity or resistance of glioma patients to the targeted therapies." (PMID 31682596, 2019). "The clinical data verified the association of the identified genes (i.e., KIF2C, CCNA2, NDC80, KIF11, KIF23, ANLN, and CENPM) with the targeted therapy response and prognosis of glioma patients." (PMID 31682596, 2019). "We also found a strong correlation between ANLN and KIF23, an independent prognostic target for glioma." (PMID 31681575, 2019).
renal cell carcinoma (4 papers, 2016 to 2022). "In another study, cytoplasmic immunoreactivity for ANLN in renal cell carcinomas was associated with a better prognosis, indicating an independent function of ANLN in the cytoplasm." (PMID 27863473, 2016).
acute respiratory distress syndrome (3 papers, 2017 to 2022). Progressive and life-threatening pulmonary distress in the absence of an underlying pulmonary condition, usually following major trauma or surgery. "ANLN has also been linked to focal acute respiratory distress syndrome (ARDS)." (PMID 30548429, 2019). "For instance, ANLN depletion leads to familial acute respiratory distress syndrome (ARDS)." (PMID 35340220, 2022).
breast tumor (3 papers, 2016 to 2024). "High nuclear fraction of ANLN in breast tumor cells was significantly associated with large tumor size, high histological grade, high proliferation rate, hormone receptor negative tumors and poor prognosis in both examined cohorts." (PMID 27863473, 2016). "Other targets have already been described, such as ANLN, which inhibits proliferation, cell migration, and tissue invasion, in addition to affecting the cell cycle, inducing apoptosis of breast tumor cells and arresting cells in the G2/M phase." (PMID 38813102, 2024). "In addition, in a panel of breast tumor lines, protein expression levels of ANLN are higher in TNBC lines as compared to luminal or Her2-overexpressed lines." (PMID 33854062, 2021).